NF1 (neurofibromin 1)
Diseases named in the same sentence as NF1 in open-access papers (continued):
Sharing a sentence is not in itself a finding about the gene and the disease.
pilocytic astrocytoma (continued). "Nf1 loss or HRas activation in oligodendrocytes did not cause optic glioma, and the mice did not display cytological atypia or increased astrocyte proliferation characteristic of pilocytic astrocytoma." (PMID 24035394, 2013). "Furthermore, neither NF1 mutations nor loss of NF1 mRNA expression were found in sporadic pilocytic astrocytomas." (PMID 19333441, 2009). "Relevant to human and mouse NF1-LGG, we also examined MDK expression in the Nf1 OPG mice and human NF1-LGG (pilocytic astrocytoma; PA) samples." (PMID 32358581, 2020). "Additionally, DNT and pilocytic astrocytoma are characterized by either kinase domain tandem duplication or hotspot missense mutations, occasionally with accompanying NF1 or PTPN11 mutation, but lacking the accompanying PIK3CA or PIK3R1 mutation that characterizes RGNT." (PMID 32859279, 2020). "However, three atypical patients (two without NF1) had undergone biopsies that revealed histological findings consistent with grade I pilocytic astrocytoma." (PMID 41440192, 2025). "The features of pilocytic astrocytoma differ considerably between patients with and without NF1." (PMID 37191728, 2023). "Indeed, there was a higher proportion of patients with three characteristics known in the literature to confer a better prognosis in the group without GHRT: the presence of NF1, pilocytic astrocytoma, and complete resection." (PMID 36612052, 2022).
schwannomatosis (59 papers, 2009 to 2026). The least frequent form of the rare genetic disorder neurofibromatosis. "Most tumors are associated with the different types of schwannomatosis and less frequently with NF1." (PMID 35741273, 2022). "The existence of a peripheral nerve tumour together with the other diagnostic criteria of schwannomatosis, NF1 or NF2 can pave the road to final diagnosis." (PMID 32506255, 2020). "The decisive diagnostic feature, which separates schwannomatosis clearly from NF1 and NF2, is the marked reduction of IENFD." (PMID 32443592, 2020). "As these neoplasms may arise in the context of tumor-predisposing syndromes, such as NF1 and the different types of schwannomatosis, it is crucial for surgical pathologists to provide a correct diagnosis in order to plan the appropriate clinical management of the patients." (PMID 35741273, 2022). "It is important to note that not only NF1 but also other related disorders such as Neurofibromatosis type 2 (NF2) and Schwannomatosis contribute to an increased risk of peripheral nerve sheath malignancies." (PMID 41002920, 2025). "These syndromes include NF1 and NF2, schwannomatosis, rhabdoid tumor predisposition syndrome, Gorlin, tuberous sclerosis, Von Hippel-Lindau, Li-Fraumeni, Turcot, and mismatch repair (MMR) deficiency syndrome." (PMID 40546517, 2025). "Another potential target is the tumor forming SCs that underlie neurofibromatosis 1 (NF1), NF2, and schwannomatosis." (PMID 38558569, 2024). "It is also important to elicit a past medical or family history of NF-1, schwannomatosis, or prior RT." (PMID 37880773, 2023). "Four of the 13 patients underwent germline genetic testing (31%): 2/2 patients with suspected schwannomatosis, 2/11 patients with clinically diagnosed NF1; including the patient that met clinical criteria for both NF1 and NF2." (PMID 35698239, 2022). "Neurofibromatoses (NF; including NF1, NF2, and schwannomatosis) are a group of rare neurogenetic disorders (NF1 occurs in approximately 1:2700 live births; NF2 and schwannomatosis occurs in approximately 1:25,000–33,000 life births, respectively)." (PMID 37213775, 2022). "There are three major genetic syndromes associated with PNST tumours—Neurofibromatosis 1 (NF1), Neurofibromatosis 2 (NF2) and Schwannomatosis." (PMID 35698239, 2022). "Schwannomatosis is less common, less well studied, and less well understood compared to NF1 and NF2." (PMID 34885143, 2021). "A landmark FDA-approved therapy has been achieved for NF1-associated PNs, but similar success for NF2 and schwannomatosis is still needed." (PMID 34885143, 2021). "Diagnosis of NF1, NF2 or schwannomatosis was established by fulfilling the necessary diagnostic criteria according to guidelines in 57/73 patients (76%); in the remaining 16 (19.5%), genetic testing confirmed the diagnosis in addition." (PMID 32506255, 2020). "Patients with neurofibromatosis 1 (NF1), NF2, and schwannomatosis are at risk for multiple nerve sheath tumors and premature mortality." (PMID 22558206, 2012). "This case highlights schwannomatosis as a rare, painful condition distinct from NF1 and NF2." (PMID 41970298, 2026). "Nine samples, in total, were represented by NF1 or schwannomatosis samples." (PMID 35008487, 2021). "In comparing NF1, NF2, and schwannomatosis with regard to the respective diagnostic features and symptoms, it is reasonable to hypothesize that C-fiber loss is indeed the cause for pain experienced by schwannomatosis patients." (PMID 32443592, 2020).
schwannomatosis (continued). "The characteristic presentation of schwannomatosis is with chronic pain associated with cutaneous and central schwannomas, but without the other features of NF1 or NF2." (PMID 30382390, 2018). "While NF2 and schwannomatosis are lower prevalence conditions than NF1, and so resources may be expected to be fewer for these patients, concerns for equity of access to healthcare necessitate attention to these disorders." (PMID 30157837, 2018). "However, whilst routine genetic analysis is able to identify around 92%−95% of variants responsible for familial cases for NF1 and NF2‐related schwannomatosis, the proportion of familial non‐NF2‐related schwannomatosis cases that can be attributed to known variants is much lower (70%−80%)." (PMID 35723634, 2022). "Next, we studied 197 samples obtained from 174 MPNSTs from 152 patients (93 NF1-associated, 16 non-syndrome-associated, 1 Schwannomatosis-associated, and 42 with unknown syndrome status given incomplete clinical history)." (PMID 31462295, 2019). "In NF1, NF2, and schwannomatosis (SWN), emerging technical advances, particularly WB-MRI as well as DWI/ADC mapping, in conjunction with clinical and genetic data, can potentially provide insight into both disease severity as well as tumor behavior." (PMID 39030374, 2025). "Neurofibromatosis type 1 (NF1, n = 4), type 2 (NF2, n = 1), schwannomatosis (n = 2) and legius syndrome (n = 1) were detected in 13% of the rare disease cohort." (PMID 39061237, 2024). "NF1 is the most common, with an incidence of 1 in 3,000 births, followed by NF2 (1 in 33,000), and schwannomatosis (1 in 60,000)." (PMID 38127915, 2023). "The predominant model of inheritance for familial non‐NF2‐related schwannomatosis is a dominant model, similar to that of NF1 and NF2‐related schwannomatosis." (PMID 35723634, 2022). "It should be emphasized that although NF1-, NF2-, and schwannomatosis-related tumors have distinct genetic origins, they share downstream activation of several molecular targets." (PMID 34604034, 2021). "The incidence rates of NF1, NF2, and schwannomatosis are 1:3,000, 1:60,000, and 1:70,000 in the general population, respectively." (PMID 33767727, 2021). "There are three types of NF: NF1 accounting for 96% of all cases, NF2 in 3%, and schwannomatosis (SWN) in <1%." (PMID 34072574, 2021). "In contrast to neurofibromatosis type 1 (NF1) and NF2, schwannomatosis is characterized by genetic heterogeneity." (PMID 32443592, 2020). "Our primary aim was to assess the ability of a non-profit foundation-sponsored clinic network to facilitate access to specialized care for patients with neurofibromatoses (NF), a group of neurogenetic disorders including NF1, NF2, and schwannomatosis (SWN)." (PMID 30157837, 2018). "Most patients seen across the network in 2015 had NF1 (n = 9418, 91.9%) and a minority had NF2 (n = 645, 6.3%) or schwannomatosis (n = 182, 1.8%)." (PMID 30157837, 2018). "As of October 14, 2015, 4476 living U.S. patients with a confirmed diagnosis of NF1, NF2, or schwannomatosis were enrolled in the patient registry." (PMID 30157837, 2018). "Fifty two of 1254 NF1 patients developed MPNST, with MPNST also occurring in 2/181 cases of schwannomatosis and 2/895 NF2 patients." (PMID 23036231, 2012). "We performed an international multicenter study of WBMRI to assess tumor burden of internal nerve sheath tumors in NF1, NF2, and schwannomatosis." (PMID 22558206, 2012). "This group included 22/52 NF1 patients (42%), 1/16 NF2 patients (6%), and 7/8 schwannomatosis patients (88%)." (PMID 22558206, 2012). "Multiple biopsies of different sites at different time periods were consistent with histology that confirmed the diagnosis of schwannomatosis, with no NF1 or NF2 features." (PMID 41970298, 2026). "Schwannomatosis is the rarest form of NF, with a prevalence that is not well established but is believed to be less common than NF1 and NF2." (PMID 40764996, 2025).
schwannomatosis (continued). "Whole-exome sequencing with the genomic DNA from peripheral blood leukocytes showed that patient 1 with INF2 p.Gly73Asp had no germline, schwannomatosis-related gene variants including 22q loss of heterozygosity (LOH), NF1, NF2, LZTR1, SMARCB1, and COQ6." (PMID 39857711, 2025). "Based on their molecular characteristics, NF is classified into NF1, NF2, and schwannomatosis." (PMID 39157066, 2024). "There are three types of NF: NF1, NF2, and schwannomatosis (SWN)." (PMID 36971896, 2023). "The most common form is NF1 (96%), followed by NF2 (3%) and the lesser known form schwannomatosis." (PMID 33767727, 2021). "Additionally, the impact of barriers to successful employment across NF1, NF2 and Schwannomatosis populations should be considered, given each presentation of the corresponding diseases are inherently different." (PMID 34020694, 2021). "There are three types in NF: NF1, NF2, and schwannomatosis (SWN)." (PMID 34072574, 2021). "For example, a multimodal approach including a relaxation response resiliency program (3RP) has been recently used in a pilot study involving patients with NF1, NF2, and schwannomatosis, with encouraging results in terms of coping strategies and quality of life." (PMID 25884655, 2015). "Unlike PNFs, PS is not strongly associated with NF1, although some cases may occur with NF2 or schwannomatosis." (PMID 41209860, 2025). "However, the term schwannomatosis or neurilemmomatosis has been used to describe patients with multiple non-vestibular schwannomas with no other stigmatas of NF-2 or NF-1." (PMID 19574706, 2009). "Unlike NF1 and NF2, Schwannomatosis primarily affects the peripheral nervous system and is characterized by chronic pain and neurological deficits." (PMID 40764996, 2025). "With only one FDA-approved therapy for NF1, no approved therapies for NF2 or schwannomatosis, and significant limitations to conventional therapeutic options in general, novel agents are greatly needed." (PMID 34885143, 2021). "Unlike NF1 and NF2, Schwannomatosis primarily affects the peripheral nervous system." (PMID 40764996, 2025).
Noonan syndrome (57 papers, 2011 to 2025). Noonan Syndrome (NS) is characterized by short stature, typical facial dysmorphism and congenital heart defects. "A 9-year, prospective, monocentric study was conducted, involving patients with NF1 pathogenic variants (PVs) and Noonan syndrome-like facial phenotype (NSLFP)." (PMID 40289159, 2025). "Missense variants affecting p.Met1149 have been associated with a mild phenotype of NF1, characterized by pigmentary features, frequent learning problems and features of NF1-Noonan syndrome." (PMID 37686284, 2023). "The NGS analysis excluded additive variants in Noonan syndrome-causing genes in our molecularly diagnosed NF1 patients with combined NF1 and Noonan-like features." (PMID 31370276, 2019). "Notably, mutations underlying Noonan syndrome and NF1 are responsible for encoding different proteins that play roles in RAS signalling." (PMID 37686284, 2023). "NF1 association with Noonan syndrome (PTPN11), Huntington’s disease (HTT), congenital myopathy (RYR1), hereditary breast cancer (BRCA1), multiple endocrine neoplasia type 2 (RET), and Jalili syndrome (association between conical rod-dystrophy and amelogenesis imperfecta) are all described." (PMID 36831560, 2023). "We included 41 articles on ASD features in NF1, Noonan syndrome (NS), Costello syndrome (CS), and cardio‐facio‐cutaneous syndrome (CFC)." (PMID 38581124, 2024). "Noonan syndrome may present with café-eu-lait macules, and if this finding, especially a large number (> 6) or size (> 5 mm) of them, which fulfills a diagnostic criteria for NF1, therefore it is better to undergo a genetic evaluation in terms of accompaniment with NF1." (PMID 36803953, 2023). "At least three (1.1%) patients were diagnosed with multiple CPSs (patient 1, trisomy 21 and tuberous sclerosis complex; patient 2, Noonan syndrome and NF1; patient 3, 13q deletion syndrome, 17q deletion syndrome, and retinoblastoma predisposition syndrome)." (PMID 34950979, 2022). "Lovastatin administered on such an acute regimen improved spatial memory impairments in both Nf1+/− mice and Noonan syndrome Ptpn11D62G/+ mice." (PMID 34311771, 2021). "The most prevalent disorders of this group are Noonan syndrome and Neurofibromatosis-1 (NF1), while LS is a rarer condition." (PMID 25884655, 2015). "The jaw lesions in Noonan syndrome and NF1 can be so extensive that they can mimic Cherubism, and therefore this diagnosis should be borne in mind and excluded (vide infra)." (PMID 25409853, 2014). "Noonan syndrome and NF1 are among the most commonly encountered germline alterations, with an incidence of 1 in 2,500—1 in 3,000 of the population." (PMID 25409853, 2014). "This was, not the case in the three patients (1, 10 and 12) with missense variants in the current cohort, they all met NIH NF1 diagnostic criteria without any apparent overlapping Noonan syndrome features." (PMID 38596211, 2024). "Some individuals have disease-causing variants occurring in both NF1 and PTPN11 (the gene most often involved in Noonan syndrome), while others may have only an NF1 variant." (PMID 37686284, 2023). "The NF1-Noonan syndrome phenotype is observed in around 12% of individuals with NF1." (PMID 37686284, 2023).
Noonan syndrome (continued). "TS, NF1 and Noonan syndrome are mechanistically distinct conditions which result in phenotypically aberrant behaviours and cognitive processes, but individuals affected by these conditions have similar overall cognitive profiles which lie within the normal range." (PMID 28694877, 2017). "In the absence of SH3BP2 mutation in an individual considered to have Cherubism, genetic screening for mutations in genes implicated in Noonan syndrome (PTPN11, SOS1, RAF1, KRAS, NRAS, and BRAF), NF1, and craniofacial cutaneous syndrome (BRAF, MAP2K1) should be undertaken." (PMID 25409853, 2014). "In addition, a rosette forming glioneuronal tumor has been previously reported in a patient with NF1, as well as one prior report of a Noonan syndrome patient with a disseminated glioneuronal tumor in leptomeninges." (PMID 22011734, 2011). "Moreover, congenital disorders including Noonan syndrome, Noonan-like/multiple giant cell lesion syndrome, NF1, LEOPARD syndrome, Costello syndrome, and Cardio-facio-cutaneous syndrome carry germline mutations that variously affect genes within the MAPK signaling cascades." (PMID 21961044, 2011). "Even in the absence of definitive signs of Noonan syndrome or NF1, screening for the relevant germline alterations should be considered, particularly if there is more than one jaw lesion, and if the lesion is extensive." (PMID 25409853, 2014). "In addition, none of these patients show the typical features of NF1–Noonan syndrome, Noonan syndrome or CFC syndrome." (PMID 30290804, 2018).